ALK (ALK receptor tyrosine kinase)
Diseases named in the same sentence as ALK in open-access papers (continued):
Sharing a sentence is not in itself a finding about the gene and the disease.
adenocarcinoma (continued). "Adenocarcinoma, the most common subtype, is often peripheral, commonly found in non-smokers, and expresses markers like TTF-1, Napsin A, and CK7, with potential mutations in EGFR and ALK that can be targeted with specific therapies." (PMID 40827171, 2025). "ML-radiogenomics classifier can help in identifying adenocarcinoma ALK rearrangement status, which may be cost-effective substitute for traditional invasive ALK status test." (PMID 40078179, 2025). "Similar to EGFR mutations, Anaplastic Lymphoma Kinase (ALK) (typically translocations) typically occurs in non-smoker NSCLC patients with adenocarcinoma histotype in approximately 3–5% of NSCLC cases." (PMID 40243903, 2025). "Use of TKIs or ALK inhibitors can be used in this subset of patients with combined adenocarcinoma." (PMID 40144596, 2025). "The most common histology seen in ALK+ NSCLC was adenocarcinoma (86.05%; n = 37)." (PMID 39807831, 2025). "Likewise, despite statistical adjustments for the number of patients with adenocarcinoma, the possibility of a sex-based imbalance in actionable driver mutations (e.g. EGFR, ALK) within our cohort and its impact on key endpoints cannot be excluded." (PMID 41218384, 2025). "Adenocarcinoma, which is often associated with environmental and genetic factors such as smoking and mutations in EGFR and ALK genes, may be more susceptible to the protective effects of Albumin, which helps maintain cellular integrity in the presence of OS." (PMID 40719999, 2025). "The median OS reported in clinical trials in the first-line setting with gefitinib (for EGFR-mutated adenocarcinoma) was 18.6 months, and with alectinib (for ALK-rearranged adenocarcinoma), it was not reached after close to 50 months of follow-up." (PMID 39123495, 2024). "An ultrasound-guided biopsy of the liver led to the diagnosis of an adenocarcinoma harboring no gene mutations based on EGFR/ROS/ALK gene direct sequencing." (PMID 38961982, 2024). "Total prevalence of ALK fusions was 2.5% (3.3% in adenocarcinoma)." (PMID 39083479, 2024). "The most prevalent alterations identified by RNA sequencing included fusions or exon skipping mutations involving therapy-associated genes MET (2.9%), ALK (1.7%), ROS1 (0.9%), and RET (0.7%), all of which were detected at a significantly higher frequency in adenocarcinoma cases." (PMID 39664186, 2024). "Such mutations usually involve fusions of the ALK gene with other genes, most commonly EML4-ALK fusions, and these mutations are predominantly found in non-smokers, younger patients, and patients with adenocarcinoma subtypes, with an incidence of 3%-5%." (PMID 39906659, 2024). "In patients with adenocarcinoma, EGFR, ALK, and ROS1 mutations as well as PD-L1 expression were mostly tested using single biomarker assays, such as Sanger sequencing, reverse transcriptase-polymerase chain reaction, immunohistochemistry, and fluorescent in situ hybridization." (PMID 39518907, 2024). "ALK rearrangements are found in about 3–5% of patients with NSCLC adenocarcinomas." (PMID 39671082, 2024). "Other frequent mutations comprise EML4 inversion rearrangement with ALK generating EML4-ALK fusion oncogene that is found in 2–7% of NSCLC cases who are mainly non-smoker adenocarcinoma patients of a median age of 55 years." (PMID 39513892, 2024). "In adenocarcinoma patients, 41.6% were positive for EGFR and/or ALK mutations." (PMID 36750899, 2023). "In this study, there were 2.3% and 1.5% of the BRAF V600E mutation and BRAF V600 non-E mutation, respectively, among adenocarcinoma without EGFR/ALK alterations." (PMID 37374289, 2023).
adenocarcinoma (continued). "Therefore, the present review aims to describe the multidisciplinary strategies in patients with mNSCLC adenocarcinoma with CNS involvement and EGFR activating mutations or ALK rearrangement." (PMID 36786970, 2023). "As an alternative algorithm, NTRK testing could be performed after histological confirmation of NSCLC and, in the case of adenocarcinoma, immunohistochemical exclusion of ALK or ROS1 alterations." (PMID 37296928, 2023). "Following the requirements of the NSCLC drug program in Poland, patients with adenocarcinoma did not have mutations in EGFR (epidermal growth factor receptor) or ALK (anaplastic lymphoma kinase) genes." (PMID 36688998, 2023). "This patient has diagnosed with stage IIIB adenocarcinoma without ALK translocation and EGFR mutation in the left lower lobe, thus three cycles of neoadjuvant Toripalimab combined with chemotherapy were used for the surgical opportunity." (PMID 37256186, 2023). "The mean age of the total population was 60.1 years old (range 32-77 years), patients (68.89%) were ≤65 years old, 55 patients (61.11%) were male, 75 patients (83.33%) were adenocarcinoma and 40 cases had gene mutation (31 were EGFR+,7 were ALK+, and 2 were ROS1+), 73(81.11%) patients with KPS ≥70." (PMID 37810984, 2023). "ALK-rearranged SCLC has a notoriously lower response to TKIs than ALK-rearranged adenocarcinoma." (PMID 38201357, 2023). "Both cases had a combined SCLC with an ALK-expression and an adenocarcinoma." (PMID 35677534, 2022). "The steepest survival increase has taken place after 2016, the time point where immunotherapy was implemented as a treatment option for the stage IV, adenocarcinoma population not harboring targetable mutations (EGFR/ALK)." (PMID 36523970, 2022). "The histologic results of pericardial localization confirmed ALK-positive adenocarcinoma." (PMID 35199053, 2022). "We present a case of ALK translocated adenocarcinoma in AYA with prolonged PFS." (PMID 35092185, 2022). "This was the time point when immunotherapy was implemented as a treatment option for the stage IV, adenocarcinoma population not harboring targetable mutations (EGFR/ALK)." (PMID 36523970, 2022). "EGFR- and ALK mutations are mainly found in patients with adenocarcinoma, and in Norway all patients with non-squamous NSCLC are routinely tested for these mutations." (PMID 36523970, 2022). "Consequently, our study reviewed data for 827 patients with adenocarcinoma to assess the association between CT and clinical characteristics and EGFR and ALK mutations." (PMID 33707479, 2021). "Several studies have shown that certain patient characteristics such as younger age, never or light smoker, signet ring cell morphology, and adenocarcinoma subtype increase the probability of finding an ALK mutation." (PMID 32876329, 2021). "In the case of adenocarcinoma, in particular, driver mutations and the corresponding drugs already exists and thus, it reacts well to targeted therapy, which includes, but is not limited to EGFR, ALK, and ROS1, resulting in good outcomes." (PMID 33422052, 2021). "In addition, considering the difficulties in establishing the exact histotype in small biopsies, it is currently recommended to perform ALK testing in tumors of a potentially mixed (adenosquamous) histology, except in those with adenocarcinoma." (PMID 33435440, 2021). "Therefore, genetic testing, including at least EGFR mutations and ALK/ROS1 rearrangements, should be performed in all NSCLC patients (in particular with adenocarcinoma) who received a diagnosis of advanced disease." (PMID 34094913, 2021). "Crizotinib was the first drug approved for adenocarcinomas harbouring ALK rearrangement." (PMID 33707479, 2021). "Notably, 46 patients (43%) had adenocarcinoma, including two patients with epidermal growth factor receptor (EGFR) mutations, four patients with anaplastic lymphoma kinase (ALK) rearrangements, and one patient with ROS1 mutation." (PMID 32057187, 2020).
adenocarcinoma (continued). "ROS1-rearranged adenocarcinomas appeared as solid tumors and were associated with young age, pericardial metastases and advanced nodal metastases relative to tumors with EGFR mutations or ALK rearrangement." (PMID 33005033, 2020). "Univariate analysis revealed that female, KPS ≥90, BMI ≥24.0, adenocarcinoma, EGFR or ALK positive, significantly decreased the death risk of patients, but ECM (especially organ numbers ≥3), BM numbers ≥4, N2~N3, and smoking (especially current smoking) increased it." (PMID 33027555, 2020). "The purpose of this study was to investigate the differences in CT characteristics and disease spread patterns between ROS1-rearranged adenocarcinomas and epidermal growth factor receptor (EGFR)-mutant or anaplastic lymphoma kinase (ALK)-rearranged adenocarcinomas." (PMID 33005033, 2020). "Patients with an age ≤ 50 years, female gender, adenocarcinoma histology, and non-smokers were more likely to harbor ALK mutation (P < 0.001, = 0.005, 0.034, and 0.004, respectively)." (PMID 33273548, 2020). "Concordant with previous molecular studies, major driver events in adenocarcinoma, namely EGFR activating mutations, ALK gene rearrangement and ROS1 gene rearrangement, were rarely present in pulmonary LELC, indicating that they were less important events in the pathogenesis of pulmonary LELC." (PMID 32726920, 2020). "All ALK positive patients were males with adenocarcinoma histology." (PMID 32460789, 2020). "Simultaneously, ALK mutation tended to be more common in older age groups, poorly-differentiated adenocarcinoma, and had no gender difference." (PMID 32429938, 2020). "Approximately 3–7% of lung tumours, mostly adenocarcinomas, harbour ALK fusions." (PMID 30953094, 2019). "In contrast, a subset of LAD patients remain without EGFR, KRAS, and ALK mutations (triple-negative (TN) adenocarcinomas)." (PMID 31093306, 2019). "Adenocarcinoma that has spread can occur due to a mutation in the genes of Kirsten rat sarcoma viral oncogene homolog (K-RAS), epidermal growth factor receptor (EGFR), and anaplastic lymphoma kinase (ALK)." (PMID 30956908, 2019). "ALK-rearrangement has been found to be associated with several distinctive clinicopathologic features including slightly more male, younger age, adenocarcinoma histology, absence of smoking history and absence of other oncogenic drivers." (PMID 31696059, 2019). "Anaplastic lymphoma kinase (ALK) rearrangement is usually observed in patients with adenocarcinoma." (PMID 29744229, 2018). "Importantly, 2HF inhibited the growth of ALK (anaplastic lymphoma kinase) gene-rearranged H3122 and H2228 adenocarcinoma NSCLC cell lines." (PMID 30546837, 2018). "Alectinib is a targeted therapy used in treating ALK-positive adenocarcinoma." (PMID 30336782, 2018). "Molecular analyses to detect epidermal growth factor receptor (EGFR) mutations and anaplastic lymphoma kinase (ALK) rearrangement identify specific subgroups of patients, often younger and non-smokers compared to other forms of adenocarcinoma." (PMID 28560038, 2017). "This is in marked contrast to NSCLC, particularly adenocarcinoma, where genome sequencing efforts have revealed the identity of numerous recurrent, actionable somatic alterations, including oncogenic EGFR mutations, as well as ALK- and ROS1 rearrangements." (PMID 29138515, 2017). "All ALK-positive patients had a histological type of adenocarcinoma." (PMID 27926526, 2017). "All of the cases with ALK rearrangement were adenocarcinomas." (PMID 28704499, 2017). "ALK rearrangement has previously been shown to be more common in light smokers or never-smokers, females, the solid predominant with mucin production adenocarcinoma subtype, and young patients." (PMID 29156778, 2017). "ALK-rearranged adenocarcinoma comprises 4–5% of adenocarcinomas." (PMID 28894699, 2017).
adenocarcinoma (continued). "Similar to EGFR mutations, ALK rearrangements are associated with distinct clinical features, including younger age at diagnosis, never of light smokers and adenocarcinoma histology." (PMID 25789627, 2015). "Furthermore, 4 ALK-rearranged adenocarcinomas were observed in patients with focal squamous differentiation." (PMID 26253541, 2015). "Thus, ALK-R in all 3 AdSqLCs were exclusively found in the adenocarcinoma component and, in mADC, the solid pattern showed ALK-R more frequently than the other patterns of growth, since 9 out of 10 ALK rearranged cases include solid growth pattern." (PMID 26422230, 2015). "In NSCLC, the ALK rearrangement has been reported to be associated with distinct clinicopathological characteristics, including a lower age at onset, adenocarcinoma histology and a history of never or light smoking." (PMID 25788996, 2015). "All recruited patients were suggested by the oncologists to screen for ALK targeted therapy based on clinical considerations (adenocarcinoma, advanced stage, young age, non- or light smoking, or previously treated with cytotoxic regimens and/or targeted therapy)." (PMID 24404167, 2014). "Similarly, ALK traslocations, present in only 4% of adenocarcinomas, are predictive of a high sensitivity to ALK-directed therapies such as crizotinib." (PMID 24625834, 2014). "This could be indirect evidence of the lower incidence of ALK rearrangements in adenocarcinomas with GGO patterns compared to adenocarcinomas of all types." (PMID 24885886, 2014). "In NSCLC, ALK rearrangement is associated with distinct clinicopathologic features, including young age at onset and adenocarcinoma histology in patients with a history of never or light smoking." (PMID 24404167, 2014). "We previously reported an ALK rearrangement rate of 6.8% in all types of adenocarcinoma." (PMID 24885886, 2014). "Clinicopathological characteristics of adenocarcinoma according to ALK rearrangement status." (PMID 23936355, 2013). "ALK rearrangement was identified in 2 patients (1.0%) from the test set and both adenocarcinomas were negative for EGFR and KRAS mutations." (PMID 23936355, 2013). "All adenocarcinomas positive for ALK were composed of mixed histological patterns." (PMID 23951022, 2013). "ALK rearrangement has been reported to be associated with younger patient age, never or light history of smoking, and adenocarcinoma histology." (PMID 23936355, 2013). "Interestingly, although the size of ALK-positive adenocarcinoma was significantly smaller than ALK-negative adenocarcinoma, the proportion of lymph node involvement was significantly more frequent." (PMID 23936355, 2013). "For instance, although EGFRwt/KRASwt adenocarcinomas with ALK rearrangements are reported to display distinct expression profiles compared with ALK-negative tumors, it remains unclear whether this is also true for CNAs and allelic imbalances." (PMID 24205279, 2013). "All 7 of the ALK-positive tumors at least harbored an adenocarcinoma component." (PMID 23341890, 2013). "In our study, none of the patients with EGFR mutation had an ALK gene rearrangement (data not shown), which is in line with the literature, indicating that EML4-ALK fusion tends to occur in adenocarcinomas lacking EGFR mutation." (PMID 23484153, 2013). "Consequently, when adjusting for an expected lower frequency of adenocarcinoma that in most of the reported ALK analysis series, we projected an initial ALK-positive frequency of ∼1.6% among unselected US NSCLC cases." (PMID 22374459, 2012). "Our results are consistent with previous studies where ALK rearrangements have been largely (but not completely) restricted to adenocarcinomas that lack EGFR or KRAS mutations." (PMID 23198868, 2012).
adenocarcinoma (continued). "In the setting of the biopsy-proven histology of primary NSCLC, patients with adenocarcinoma and/or known high-risk oncogenic driver mutations (EGFR, ALK), as well as patients of young age, might be considered to undergo BI due to the higher incidence of BM in this population." (PMID 39941379, 2025). "No EGFR or ALK mutation were detected in patients with adenocarcinoma." (PMID 32833338, 2020). "Furthermore, useful data on EGFR‐, KRAS‐, ALK‐ and ROS‐mutational status of the adenocarcinoma subcohort is not present and fresh frozen tissue is no more attainable." (PMID 31760702, 2020). "If the EGFR mutational status of an EBUS-GS specimen is negative, a false-negative should be considered when the sample volume is small, particularly if the patient is at risk of EGFR or ALK mutation (has an adenocarcinoma, is a female East Asian, or is a never-smoker)." (PMID 30807604, 2019). "Although we collected enough GGO nodules with EGFR mutations in exons 19 and 21, we could not collect sufficient numbers of samples with ALK rearrangement due to the inherent limitation that adenocarcinoma with ALK rearrangement tends to present as solid nodules in chest CT." (PMID 24885886, 2014). "However, the role of ALK rearrangement, another potent driver mutation in adenocarcinoma, has not been described in GGO nodules." (PMID 24885886, 2014). "The growing number of detected tyrosine kinase fusions in predominantly EGFRwt/KRASwt adenocarcinomas (including ALK, RET, and ROS1) are also becoming increasingly important in the therapeutic setting, as these alterations are/may become targets for specialized molecular agents." (PMID 24205279, 2013). "Importantly, although EGFR and ALK mutations are found mostly in patients with history of no smoking or light smoking who have adenocarcinoma, genotyping should be offered to all patients with advanced NSCLC if treatment with specific TKIs is available." (PMID 21444946, 2011). "The consistent result was seen with younger age, female sex, adenocarcinoma, p-stage II, positive EGFR/ALK, and ICI by multivariate analysis." (PMID 40676423, 2025). "Of the 49 patients randomized, 80% had adenocarcinoma, 84% were EGFR or ALK wild-type, and 94% had synchronous metastases." (PMID 40805152, 2025). "In adenocarcinoma subgroups, EGFR-mutant tumors most often metastasized to the brain (55.6%), KRAS-mutant tumors to the liver (44.4%), and ALK-rearranged tumors to bone (100%)." (PMID 41294679, 2025). "Within adenocarcinoma, exploratory molecular subgroups showed: EGFR 10/18 (55.6%) brain; KRAS 4/9 (44.4%) liver; ALK 3/3 (100%) bone." (PMID 41294679, 2025). "Anaplastic lymphoma kinase gene (ALK) fusion occurs in approximately 5% of non-small cell lung cancer (NSCLC) cases and most frequently in adenocarcinoma." (PMID 40224190, 2025). "Testing for anaplastic lymphoma kinase (ALK) and ROS1 rearrangements is recommended in adenocarcinoma." (PMID 39199613, 2024). "In analyses of only those patients with adenocarcinoma, the median CEA level was 5.2 ng/mL in the ALK group and 17.3 ng/mL in the EGFR group, with a statistically significant difference (p = 0.007)." (PMID 38400801, 2024). "Several biomarker-guided therapies have been approved, targeting genes frequently altered in adenocarcinoma, such as EGFR, BRAF, MET, ALK, ROS1, RET and NTRK." (PMID 39199558, 2024). "For adenocarcinoma cases only, CEA positivity was also significantly lower in the ALK group (49%) compared with 71% in the EGFR group (p < 0.001)." (PMID 38400801, 2024). "However, as the EC regimen did not address the ALK-positive adenocarcinoma component, there was a risk that the ALK-positive adenocarcinoma could grow and metastasize as a non-dominant subclone, warranting an ALK-targeted approach to prevent progression." (PMID 39723252, 2024). "This case series describes two patients diagnosed with stage IV adenocarcinoma with coexisting EGFR and ALK rearrangements." (PMID 38046784, 2023).